CD274 (CD274 molecule)
Diseases named in the same sentence as CD274 in open-access papers (continued):
Sharing a sentence is not in itself a finding about the gene and the disease.
tumor (continued). "In 369 samples with PD-L1 IHC data, we found that the percentage of PD-L1 positive tumor cells had a moderate correlation (ρ = 0.65) with the mRNA level of PD-L1 (CD274) assessed by EdgeSeq PIP, which was comparable to its association with RNA-seq (ρ = 0.69)." (PMID 35712667, 2022). "The potential implication of IRFs in tumor immunity was investigated in terms of tumor-infiltrating immune cells, a pair of immune checkpoint genes (CD274 and PDCD1), and ESTIMATE-Stromal-Immune score." (PMID 35664436, 2022). "The aim of this study is to uncover processes inhibiting PDCD1/CD274 expression thereby enhancing anti‐tumour immune responses." (PMID 35802807, 2022). "The expression of CD274 mRNA was slightly significantly lower in primary tumor tissues compared to the normal tissues (P = 0.049305)." (PMID 35717238, 2022). "Programmed cell death-1 (PD-1, also called CD279)/programmed death-ligand 1 (PD-L1, also known as CD274) is a pair of critical immune checkpoints (IC) and tumor cells can inhibit the killing effect of the immune system by activating the PD-1/PD-L1 axis." (PMID 35223466, 2022). "Cytotoxic T lymphocyte-associated protein 4 (CTLA4) and programmed cell death ligand 1 PD-L1 (known as CD274) are immune checkpoint proteins expressed on tumor cells and tumor-infiltrating immune cells." (PMID 36230798, 2022). "It was discovered that IP-score was closely associated with PDCD1, CD274, CTLA-4, and LAG3 expression levels in urinary solid tumours, indicating that IP-score was closely associated with tumour escape and immune depletion." (PMID 36700205, 2022). "Next, considering the potential tumor suppressor role of EPHX3 in HNSCC, we examined the association between EPHX3 and CD274, IL1B, IL1A, PDCD1, and PDCD1LG2." (PMID 35401746, 2022). "Most of the tumor immunity-related genes, including PD-L1 (CD274), PD-1 (CD279), CTLA4, and B7H3 (CD276), were at a higher expression level in the high-risk group." (PMID 36267281, 2022). "Important immunological checkpoints involved in tumor immune escape include CD274, IL1B, IL1A, PDCD1, PDCD1LG2, and SIRPA." (PMID 35401746, 2022). "To explore mechanism of GIMAP4 underlying tumor-immune regulation, we calculated the correlations between GIMAP4 and 5 ICPs (CD274, CTLA4, TIGIT, LAG3, and PDCD1) and identified similar trends in their expression." (PMID 36246963, 2022). "First, the retrospective design of the study prevented us from properly investigating various clinical and histopathological parameters, including BRAF, MSI, PD-1 (CD279), PD-L1 (CD274), and the immunological profiling of the tumor." (PMID 36013050, 2022). "Conversely, the knockout of genes that promote tumor immune escape (such as CD274) can enhance the sensitivity of tumor cells to T cell-mediated killing, leading to the depletion of sgRNAs (these genes were named as resistor genes hereafter)." (PMID 34980132, 2022). "In conclusion, in primary tumor samples in TCGA, multiple immune checkpoint molecules, including CD274, correlated positively with inflammatory and immune response-associated pathways, a PD-L1 signature, and with mesenchymal behavior." (PMID 36354714, 2022). "CD274 is a classic immune checkpoint gene that exhibits constitutive expression in tumor cells and can be targeted by clinically approved drugs." (PMID 36248853, 2022). "In other words, the CD274 expression level in advanced tumor samples was significantly lower compared to that in the early tumor samples." (PMID 36157232, 2022). "The present study aimed to develop a more rapid qRT-PCR assay to measure CD274 mRNA expression that closely correlates with PD-L1 IHC and save archival tumor tissues for other IHC assays in the same patient." (PMID 35574404, 2022). "We also compared its predictive power with existing biomarkers, including the TIDE score, the MSI score, tumor mutational burden (TMB), and CD274 (PD-L1), by calculating the AUC (area under the ROC curve)." (PMID 36497434, 2022).
tumor (continued). "PD-L1 (also known as B7H1 and CD274) is a 40-kDa type 1 transmembrane protein, expressed in a variety of cells and has the greatest immunosuppressive effect when it is expressed on tumor cells." (PMID 35090497, 2022). "Of note, CDK16 knockdown led to a reduced expression of MYC proto‐oncogene, bHLH transcription factor (MYC) and CD274 molecule (PD‐L1), which in turn enhanced the tumor‐suppressive effects of senescent cancer cells." (PMID 34687270, 2022). "Previous studies showed that PDCD1 (PD1), CD274 (PDL1), and CTLA-4 were closely associated with immune escape in the tumor microenvironment." (PMID 35273591, 2022). "CD274, also known as programmed cell death ligand 1 (PD-L1), is an immune checkpoint molecule expressed in tumor cells that binds to programmed death 1 (PD1) in T cells." (PMID 36248886, 2022). "PD-L1, also known as CD279, is a type 1 transmembrane glycoprotein encoded by the CD274 gene, widely expressed in tumour cells, and weakly expressed in some activated T and B cells and dendritic cells." (PMID 36140252, 2022). "First, IRF1 is reported as an important transcription factor to regulate tumour cell PD‐L1 expression by binding to CD274 promoter." (PMID 35083874, 2022). "In particular, the positive prognostic impact of tumor lymphocytes in patients with dMMR CRC was denied by the presence of high-level CD274 in the tumors." (PMID 36013315, 2022). "PDL1 (CD274) is frequently observed in tumor cells, and PD1 (CD279) is expressed in immune cells (T lymphocytes, macrophages, and others)." (PMID 36238642, 2022). "The CIBERSORT database and Spearman correlation analysis indicated that SLC1A5 was correlated with eight types of tumor-infiltrating immune cells and immune checkpoints, including PD-L1(CD-274) and PD-1(PDCD1)." (PMID 35305616, 2022). "PD-1 is a receptor for programmed death ligand 1 (PD-L1, CD274, B7-H1), which is expressed on the surface of tumor cells." (PMID 35026984, 2022). "Specifically, we showed that CD274 copy number gain of ploidy +2 (CN ≥ 4 in diploid tumor samples) is an optimal cutoff to predict positive response to ICI in non-squamous NSCLC." (PMID 35598202, 2022). "We also investigated correlations between CD274 and PDCD1LG2 and immunotherapeutic biomarkers, including mismatch repair (MMR), tumor mutation burden (TMB), microsatellite instability (MSI), and DNA methylation." (PMID 36276934, 2022). "P2RX1 expression was significantly positively correlated with PDCD1 (r = 0.507, p = 3.84e-66), CTLA4 (r = 0.455, p = 6.07e-52) and CD274 (r = 0.351, p = 3.26e-30) in BC after adjusted by tumor purity." (PMID 35585027, 2022). "In the aspect of predicting the efficacy of immunotherapy, the low macrophage abundance group had a higher tumor mutational burden (TMB) and more PD-L1 (CD274) expression." (PMID 34414187, 2021). "SPOP can promote the ubiquitination modification of PD‐L1 (CD274), which in turn regulates tumor development, and that PD‐L1 gene is a DEG in the treatment of EAC." (PMID 34586738, 2021). "ChIP-Seq traces generated from the ENCODE database showed a large accumulation of H3K4me2 in the CD47/CD274 promoter regions of many tumor cells." (PMID 33731702, 2021). "Immune checkpoints expressed in tumor cells, including PD-L1 (CD274), galectin 9 (LGALS9), HVEM (TNFRSF14), exhaust CD8+ T cells and reduce CD8+ T-derived cytotoxicity." (PMID 34685495, 2021). "PD-L1 (also known as CD274 or B7H1) is principally expressed on tumor and antigen-presenting cells (APCs)." (PMID 34065396, 2021). "The T cell inflamed tumor biomarker CD274 (PD-L1) was significantly upregulated in the LsS4D in addition to BATF3, CD247 (CD3ζ), CD80 among others." (PMID 33776991, 2021).
tumor (continued). "Programmed death ligand 1 (PD-L1, also termed B7-H1 or CD274) is commonly expressed by tumor cells and binds to the programmed death 1 (PD-1) immune checkpoint receptor on T cells." (PMID 33653969, 2021). "EC Shb KO reduced the expression of immune checkpoint genes Ctla4 and PD-L1 (Cd274) in tumor CD45+ cells, suggesting that the observed reduction in the expression of these genes plays a minor role in the observed increase in metastasis." (PMID 34768912, 2021). "Programmed death-ligand 1 (PD-L1), also known as CD274, is a cell surface membrane-bound ligand associated with many types of tumour cells." (PMID 33789758, 2021). "Amplification of CD274, leading to overexpression of PD-L1 in tumor cells, is an interesting characteristic of GC, particularly EBV (+) GC24,25." (PMID 33479394, 2021). "Though the expression of CD274/PD-L1 was gradually elevated in TCR-TMART-1 with increased tumor PD-L1, there was limited correlation between CD274 expression in T cells and T cell death (data not shown)." (PMID 33754038, 2021). "PD-L1, also known as B7-H1 and CD274, is a transmembrane protein commonly expressed on the surface of tumor cells." (PMID 33849634, 2021). "Eight tumor-related immunosuppressive molecules, CD274, CTLA4, HAVCR2, LAG3, PDCD1 (PD1), PDCD1LG2, SIGLEC15, and TIGIT, had higher expression in HNSCC tumor tissues compared with HNSCC normal tissues." (PMID 34917682, 2021). "Tumor mutation burden (TMB) and PD-L1 (CD274) expression are currently the main predictors of immunotherapy efficacy." (PMID 34414187, 2021). "Programmed death ligand-1 (CD274), is enriched mainly in antigen-presenting cells and tumor cell surfaces and rarely in normal samples, which makes it differentially functional with other co-inhibitory pathways." (PMID 34721986, 2021). "PD‐L1 (CD274) expression plays a vital role in tumor immune escape and is also a predictive marker for therapeutic efficacy of immune checkpoint inhibitors (ICIs)." (PMID 34590792, 2021). "Programmed cell death-ligand 1 (PD-L1, designated CD274, B7-H1) is a 44 kDa transmembrane protein expressed on T cells, B cells, macrophages, and dendritic cells as well as on tumor cells, including CRCs." (PMID 33466394, 2021). "Cytotoxic T Lymphocyte antigen 4 (CTLA-4), Programmed Cell Death 1 (PD-1), and Programmed Cell Death Ligand 1 (PD-L1, also known as B7-H1 or CD274) pathways are the best known immune checkpoint pathways for immune responses within the tumor microenvironment." (PMID 33823818, 2021). "RPPA profiling revealed a significant (false discovery rate (FDR) < 0.05) upregulation of CD274 (PD-L1) in the 344SQ KP tumors when tumor-bearing mice were treated with AZD6244." (PMID 33972557, 2021). "Its ligand, programmed death-ligand 1 (PD-L1, also known as CD274), is mainly expressed on tumor cells in the tumor microenvironment." (PMID 34522232, 2021). "Later, the tumor-cell inhibitory marker PD-L1 (CD274, previously known as B7-H1) was discovered in 1999-2000 and PD-L2 (CD273, previously known as B7-DC) in 2001 and was considered even much better control over immune cell checkpoint-based therapeutic targets." (PMID 34571899, 2021). "Programmed cell death 1 (PD-1, also known as PDCD1) on the surface of CD8+ T cells binds to programmed cell death ligand 1 (PD-L1, also known as CD274) produced by tumor tissue, leading to a limited host immune response." (PMID 33465047, 2021). "CAFs were associated with tumor proliferation, elevated memory CD4+T cells and high CD274 (encoding PD-L1) expression." (PMID 34408230, 2021). "Ligands for checkpoint proteins were also correlated with a mesenchymal-like score, including CD274 (PD-L1) that is expressed by tumor cells and several immune cells in the TME." (PMID 34832904, 2021). "As a peripheral checkpoint, PD-1 can associated with its ligands PD-L1 or B7-H1/CD274, PDL2 or B7-DC/CD273 to target tumor cells." (PMID 34211835, 2021).
tumor (continued). "As expected, a higher PSMC5 level was significantly linked to expression of CD274 (PD-L1), CTLA-4, and IDO1 in CRC tumor cells, indicating a potential role of inhibiting PSMC5 in immune checkpoint blockade (ICB) therapy." (PMID 34336824, 2021). "We analyzed the area under the ROC curve (AUC) for CD40 expression in comparison with existing biomarker signatures, including tumor mutational burden (TMB), CD274 (PD-L1) and CD8, as a tool for predicting response to immunotherapy." (PMID 34758832, 2021). "Regarding the high frequency of immune cell infiltration-related lncRNA HCP5, the lncRNA has been reported to sponge miR-150-5p and upregulated the expression of PD-L1/CD274, thus promoting tumor growth and affecting immunotherapy." (PMID 34222227, 2021). "PD-L1, also known as CD274 or B7-H1, is a key protein expressed by tumor cells for suppressive immune response, and its receptor PD-1 (also known as CD279) is constitutively expressed in immune cells as a safety mechanism for controlling immune response." (PMID 34625124, 2021). "We combined the data of tumor-infiltrating lymphocytes, i.e., ICSs, and the CD274 expression of immune cells, as suggested and done in previous studies." (PMID 34680073, 2021). "Since PD-L1 is often upregulated in tumor tissues, particular attention was given to observe a possible link between its expression and CD274 gene amplification." (PMID 34503236, 2021). "The EMT signaling upregulates the immune checkpoint molecule PD1 ligand (PDL1, CD274) expression in tumor cells dependent on the PI3K/AKT and MEK/ERK pathways, and PDL1 functionally regulates EMT through the RAS/ERK pathway." (PMID 33535613, 2021). "A prominent example of such a tumor-mediated attenuation of immune surveillance is the interaction of the inducible ligand PD-L1 (B7-H1, CD274) to its receptor PD-1, which is expressed on tumor infiltrating lymphocytes (TILs) and also tumor cells." (PMID 34102454, 2021). "CD274 is found in exosomes in the plasma of tumor patients, where it plays a role in tumor progression." (PMID 34326687, 2021). "ZDHHC16 expression was significantly positive associated with clinicopathological stage, tumor grade and ICB immunotherapy key genes (i.e., CD274, CTLA4, HAVCR2 and PDCD1, etc.)." (PMID 33794886, 2021). "Here, we reveal that high expression of PD-L1 by tumor cells in EBV (+) GC is due to high levels of CD274 focal amplification in the absence of CD8 lymphocyte infiltration." (PMID 33479394, 2021). "The small number of S/R RCC tumors that harbored CD274 gene amplification and had PD-L1 expression data available all expressed tumor cell PD-L1." (PMID 33547292, 2021). "We saw a higher expression of PD-L1 (CD274) in low NE-score SCLCs for 3 out of 4 primary tumor data sets." (PMID 33750914, 2021). "HSPB1 and KRT18 were the tumor marker genes investigated, and patients were classified into PD-L1low and PD-L1high groups based on the relative expression of CD274 (Cutoff = 0.003)." (PMID 33754038, 2021). "A high rate of de novo somatic mutations leads to high levels of neoantigens, causing abundant tumor-infiltrating lymphocytes, which are counterbalanced by the increased expression of immune checkpoint molecules, such as PDCD1 and CD274." (PMID 34680073, 2021). "Third, aged Mb macrophages upregulate expression of immunosuppressive ligands Cd274/Pd-l1 and Lilrb4/Ilt3, thus, potentially inhibiting NK cells and T cells, creating a pro-tumor immune microenvironment." (PMID 33378681, 2020). "In the context of tumor microenvironments, cells including macrophages, DC, myeloid-derived suppressor cells, regulatory T cells and endothelial cells can upregulate PD-L1/CD274 due to inflammation responses." (PMID 33066260, 2020). "Accordingly, RNAseq revealed a significant increase in CD274 in canine tumor cells (Log2 fold-change = 1.527, P-value = 0.001), which was validated by qRT-PCR." (PMID 33142242, 2020).
tumor (continued). "Multiple studies have shown that EBVaGC is commonly characterized by high lymphocytic infiltration in the tumor microenvironment, coupled with overexpression of immune-related genes, including PD-L1 (also known as CD274)." (PMID 34212113, 2020). "Some studies showed that hypoxia-activated HIF-1α upregulates PD-L1 expression on tumor cells and immune cells by binding directly to a hypoxia response element in the proximal promoter of CD274 (encoding PD-L1)." (PMID 32775303, 2020). "We found the up-regulation of cytotoxic cells, CD274 (PD-L1), PDCD1, CTLA-4, HAVCR2, IFN-γ, and so on in high-risk group, whereas opposite result was observed only in absolute tumor purity." (PMID 32537435, 2020). "Supporting the notion, PD-L1 (encoded by CD274) is the most significantly upregulated protein in LATS2-mutant MPM, and LATS1/2 deletion has recently been shown to enhance anti-tumor immune responses." (PMID 32824422, 2020). "PD-1 interacts with two ligands: PD-L1 (CD274), expressed on the cell surface of activated lymphocytes (T, B, and NK), peripheral tissues and organs, and to a greater extent by tumor cells, and PD-L2, expressed primarily by macrophages and dendritic cells." (PMID 32138216, 2020). "Programmed death-ligand 1 (PD-L1, also known as CD274) is a membrane-bound ligand found on the cell surface of many tumor cell types that are upregulated in oncogenic lesions." (PMID 32322256, 2020). "The only case with amplification of both CD274 and PDCD1LG2 loci had correspondingly high mRNA expression of PD-L1, as well as strong PD-L1 and high PD-L2 protein expression within the tumor fields." (PMID 33424844, 2020). "The CD274 promoter is the target of several transcription factors since a fine-tuning of PD-L1 expression on tumor cells is needed." (PMID 33114576, 2020). "Within the tumor, expression of immunosuppressive molecules, including Cd274 (PDL1) and Arg1, increased at later time points." (PMID 32433953, 2020). "Copy number alterations (CNA) of PD-L1 (CD274) gene were evaluated in tumor tissues collected from 126 patients in the SAFIR-02 IMMUNOTRIAL." (PMID 36046385, 2020). "Utilizing the specific binding between HPV capsid and α6 integrin over-expressed in TNBC17, PEGylated HPV16 L1 protein is assembled with siRNA oligonucleotides (for Cd274 knockdown) for inhibiting the expression of tumor-specific PDL118,19." (PMID 32332752, 2020). "The results showed that the level of CD274 varies at tumor stages in COAD, ESCA, READ, SKCM, and THCA, mostly between early (stage I and II) and late-stage (stage III and IV) patients." (PMID 33585244, 2020). "In contrast, the INT subtype, associated with a higher tumor mutation burden (TMB), enrichment in upregulated CD274 and aberrant DNA damage repair pathway, was predicted to respond better to immune checkpoint inhibitors." (PMID 32785164, 2020). "In agreement with the mouse data, we found that in human tumor-infiltrating macrophages CD274 (PD-L1) gene transcription correlates significantly with the IRE1α gene signature." (PMID 32520957, 2020). "Checkpoint ligand-receptor pairs (e.g., tumor Treg CD80-Th17 cell CTLA4 and tumor Treg CD274-Th17 cell PDCD1) were identified." (PMID 33584715, 2020). "Expression of CMTM6 was reported to limit anti-tumor immunity via regulating abundance and localization of programmed death ligand-1 (PDL1/CD274) at the surface of cancer cells, at least in vitro." (PMID 32908139, 2020). "We varied this filter threshold from zero to 1,000 raw counts and then included the pathway activity scores in multiple OLS linear models to predict CD274 across tumor-infiltrating macrophage samples." (PMID 32520957, 2020). "Expression of CMTM6 can affect the presence of programmed death ligand-1 (PDL1/CD274) at the surface of cells in a tumor environment at least in vitro, a possible mechanism to regulate anti-tumor immunity." (PMID 32908139, 2020).